YAP1 (Yes1 associated transcriptional regulator)
Diseases named in the same sentence as YAP1 in open-access papers (continued):
Sharing a sentence is not in itself a finding about the gene and the disease.
pancreatic cancer (continued). "SDCBP inhibits the CK1δ/ε-mediated phosphorylation of YAP at Ser384/Ser387 by binding to YAP1, thereby blocking β-TrCP-dependent ubiquitin-mediated degradation of YAP1 and suppressing pancreatic cancer proliferation and metastasis." (PMID 41463025, 2025). "In pancreatic cancer, PKCiota upregulated sp1, promoted sp1 to bind with the promoter of YAP1 and transactivated YAP1 expression, and finally promoted pancreatic carcinogenesis." (PMID 38247539, 2024). "Clinical samples of human pancreatic cancer showed significantly increased YAP1 levels compared to those of the normal population (normal samples: n = 4, pancreatic primary tumor samples: n = 178)." (PMID 39458993, 2024). "The high expression of YAP1 was negatively correlated with survival prognosis and was confirmed in various human pancreatic cancer cell lines (HPNE, BXPC-3, PANC-1, Capan-2, and Miapaca-2)." (PMID 39458993, 2024). "Multiple genes regulated by YAP1 are related to the unfavorable survival of pancreatic cancer patients, such as FOSL1, CCND1, and NOTCH2." (PMID 36735162, 2023). "We first found a significantly positive relationship between GPRC5A and YAP1 in pancreatic cancer using the GEPIA database." (PMID 36735162, 2023). "In summary, our findings demonstrated that inhibiting YAP1 was beneficial in disrupting the adverse effects of GPRC5A on pancreatic cancer cells." (PMID 36735162, 2023). "Research has indicated that the co-activation of ZEB1 and YAP1 can trigger the transcriptional regulation of ITGA3 through the binding sites of YAP1/TEAD in both pancreatic cancer cells and tissues." (PMID 37881431, 2023). "Next, we examined YAP1 expression in pancreatic cancer cell lines and normal cells at both the mRNA and protein levels and found that the expression of YAP1 was positively related to GPRC5A expression." (PMID 36735162, 2023). "To explore the impact of GPRC5A on YAP1, we evaluated the relationship between GPRC5A and YAP1 downstream target genes in pancreatic cancer patients." (PMID 36735162, 2023). "Our experiments demonstrated that disrupting YAP1 expression almost completely inhibited the effect of GPRC5A on pancreatic cancer cells." (PMID 36735162, 2023). "Survival analysis showed that the patients with high expression of YAP1 in pancreatic cancer have a poor OS (MST: 394 vs. 691 days, P < 0.0001) and DFS (MST: 371 vs. 542 days, P=0.026) prognosis." (PMID 35911146, 2022). "By excluding patients undergoing chemotherapy or radiation, the data showed that the YAP1 expression influences overall survival only in pancreatic cancer (MST: 278 vs. 684 days, P < 0.0001)." (PMID 35911146, 2022). "The expression of YAP1 can more accurately predict the prognosis of patients with pancreatic cancer." (PMID 35911146, 2022). "Consistent with the dissociated expression between the mRNA and protein of YAP1‐1 and YAP‐2 isoforms in pancreatic cancer cells, we observed lower expression of YAP1‐2 protein in NSCLC, despite its higher expression at mRNA level compared to YAP1‐1." (PMID 35014181, 2022). "The YAP1 expression is closely related to prognosis in patients with esophageal and pancreatic cancer." (PMID 35911146, 2022). "GATA4 knockdown reversed the inhibition of YAP1 and proliferation and invasion of abilities of pancreatic cancer cells induced by WDR3 silencing and reversed the upregulation of YAP1 expression induced by WDR3 overexpression." (PMID 33648545, 2021). "Consistently, the GEPIA searching result showed a positive correlation between WDR3 and YAP1 mRNA expression levels in pancreatic cancer patient specimens." (PMID 33648545, 2021). "All these genes are upregulated in pancreatic cancer, and seven of them are significantly associated with unfavorable prognosis (MET, YAP1, PTPN14, EPS8, AHNAK, RALB, and AFAP1)." (PMID 34957301, 2021).
pancreatic cancer (continued). "We determined the potential differential impact of AKT signaling on YAP1 isoform stability and subcellular location in pancreatic cancer cells by examining their expression in response to TGF-β treatment, both with and without the AKT inhibitor." (PMID 34094936, 2021). "Our results suggest that YAP1 expression is related to pancreatic cancer and the immune microenvironment." (PMID 34150844, 2021). "In line with our result, the level of YAP1 determined by quantitative RT-PCR was increased 2.5-fold in pancreatic tumors in comparison to the normal pancreas." (PMID 34257617, 2021). "Our findings suggested that YAP1 has prognostic value in several types of cancers, especially pancreatic cancer, and the YAP1 expression patterns and prognostic value differed among cancer types." (PMID 34150844, 2021). "Using the KM plotter, GEPIA, and TCGA databases, we found that high YAP1 expression was significantly related to a poorer prognosis in pancreatic cancer." (PMID 34150844, 2021). "YAP1 is the key downstream regulator in the Hippo pathway that exhibits upregulated expression in pancreatic cancer." (PMID 33648545, 2021). "We next used LOGpc to explore the link between YAP1 expression and outcomes for patients with breast, colorectal, esophageal, gastric, lung, and pancreatic cancers." (PMID 34150844, 2021). "We analyzed the expression of YAP1 as well as its prognostic value and correlations with immune infiltrates in various cancers, with a focus on pancreatic cancer." (PMID 34150844, 2021). "We found that YAP1 expression was significantly related to outcomes in multiple types of cancer based on data from The Cancer Genome Atlas, particularly in pancreatic cancer." (PMID 34150844, 2021). "Our results showed that both YAP1-1 and YAP1-2 isoforms are important mediators in the EMT process of pancreatic cancer." (PMID 34094936, 2021). "Consistent with our result from multiplatform analysis, they found the high level of YAP1 mRNA was an independent biomarker for poor prognosis in pancreas tumors." (PMID 34257617, 2021). "In summary, YAP1 can be a valuable prognostic biomarker as well as a crucial regulator of immune cell infiltration in patients with pancreatic cancer." (PMID 34150844, 2021). "Aberrant transcriptional activity of YAP1 has crucial roles in pancreatic tumor cell biology, including roles in growth, epithelial-mesenchymal transition (EMT), microenvironmental signaling transduction, and drug resistance." (PMID 33648545, 2021). "In short, the results proved that the YAP1-2 is more potent than YAP1-1 in mediating TGFβ-induced EMT in pancreatic cancer cells." (PMID 34094936, 2021). "Another important aspect of this research was the finding that the expression of YAP1 is significantly correlated with diverse immune cell infiltration levels in multiple cancer types, especially in pancreatic cancer." (PMID 34150844, 2021). "TRIM29 can also directly bind to Yes-associated protein 1 (YAP1) to reduce its ubiquitination and degradation, and thus promote the proliferation of pancreatic cancer cells." (PMID 34988104, 2021). "Lnc-EPIC1 lost its ability to promote proliferation and growth of YAP1-silenced pancreatic cancer cells." (PMID 34178644, 2021). "YAP-1 has also been demonstrated to be involved in tumor initiation and progression in pancreatic cancer." (PMID 34957301, 2021). "In brief, all these data showed that WDR3 knockdown enhanced the anti-pancreatic cancer effect of YAP1 inhibition both in vitro and in vivo." (PMID 33648545, 2021). "In an inducible KRASG12D pancreatic cancer mouse model, the amplification and overexpression of the transcriptional coactivator Yap1 has been demonstrated to be a potential KRAS independent bypass mechanism." (PMID 33777798, 2021). "YAP1 maintained the expression of MYC, whereas knockout of YAP1 caused considerable downregulation of MYC that resulted in growth arrest of pancreatic cancer cells and apoptosis." (PMID 34178644, 2021).
pancreatic cancer (continued). "Ingenuity Pathway Analysis was applied to outline the interaction network for YAP1 in connection to the pancreatic tumor microenvironment." (PMID 32054505, 2020). "Characterized by six unique peptides, YAP1 was annotated as the top upregulated protein in pancreatic tumor specimens (log2 fold change 6.4; p = 5E−06)." (PMID 32054505, 2020). "In a previous study, we identified YAP1 as a differentially expressed protein between pancreatic cancer and normal controls using MS-based proteomics profiling." (PMID 32054505, 2020). "The protein expression levels of YAP1 were analyzed using immunohistochemistry staining on TMA sections constructed from 140 pancreatic tumors." (PMID 32054505, 2020). "YAP1 is thus considered as a clinically and biologically relevant biomarker derived from pancreatic cancer tissue." (PMID 32054505, 2020). "YAP1 was selected as a possible biomarker for pancreatic cancer from global protein sequencing of fresh frozen pancreatic cancer tissue samples and normal pancreas controls." (PMID 32054505, 2020). "In conclusion, these data demonstrate that metformin in combination with LW6 impairs pancreatic cancer cells and inhibits nuclear localization of YAP1." (PMID 31897243, 2020). "By targeting YAP1, miR-186 inhibited proliferation, migration, and invasion of pancreatic cancer and hepatocellular carcinoma cells." (PMID 32195180, 2020). "The expression of YAP1 target gene products was evaluated after treatment of the pancreatic cancer cell line Panc-1 with three substances interrupting YAP–TEAD interaction, including Super-TDU, Verteporfin and CA3." (PMID 32054505, 2020). "To understand the biological role of YAP1 in pancreatic cancer, we performed bioinformatic analyses of protein networks." (PMID 32054505, 2020). "Mass spectrometry based proteomics showed that YAP1 is the top upregulated protein in pancreatic cancer tissue when compared to normal controls (log2 fold change 6.4; p = 5E−06)." (PMID 32054505, 2020). "To assess the prognostic significance of YAP1, we analyzed mRNA expression level data and patient survival based on 176 pancreatic cancer patients included in TCGA." (PMID 32054505, 2020). "Using the patient derived pancreatic cancer cell line Panc-1, we evaluated the effect of substances designed to inhibit the YAP1/TEAD mediated gene transcription." (PMID 32054505, 2020). "In the present study, we investigate the prognostic utility and the biological significance of YAP1 in pancreatic cancer using large and clinically well-annotated cohorts, complemented by bioinformatics and in vitro experimental analyses." (PMID 32054505, 2020). "O-GlcNAc transferase (OGT) directly induces O-GlcNAcylation at YAP1 Ser109 and Thr241, and potentiates the pro-proliferation activity of YAP1 in pancreatic cancer and liver cancer cells." (PMID 32390875, 2020). "In vitro, OGT KO inhibits O-GlcNAcylation at the YAP1 Ser109, thereby inhibiting cell-colony formation in pancreatic cancer; in vivo, OGT knockdown downregulates tumor growth." (PMID 32390875, 2020). "This pathway when targeted with YAP1 offers a feasible treatment strategy for developing new therapeutics for treating pancreatic cancer." (PMID 31602269, 2019). "YAP1 activation promotes epithelial–mesenchymal transition (EMT) and is associated with liver metastasis in pancreatic cancer, thereby inducing progression to a more aggressive phenotype." (PMID 31575084, 2019). "Further study is needed to evaluate the role of the fibrotic process in tumor progression and metastasis in YAP1–NMU-expressing pancreatic cancer." (PMID 31575084, 2019). "The results showed that NMU and YAP1 mRNA expression levels were higher in metastatic fat and liver tumors than in primary pancreatic tumors." (PMID 31575084, 2019). "Analysis of the combined effect of NMU and YAP1 on clinical outcomes showed that high NMU and YAP1 expression was associated with poor mean survival in pancreatic cancer patients." (PMID 31575084, 2019).
pancreatic cancer (continued). "In this study, we performed a correlation analysis of multiple independent databases to identify potential targets of YAP1 in pancreatic cancer." (PMID 31575084, 2019). "M2 TAMs have been shown to be associated with YAP1 signaling, which correlated with tumorigenesis in several cancer types, and recent studies have discovered the involvement of YAP1/HIF-α pathway in promoting cancer stem cells in pancreatic cancer." (PMID 30925924, 2019). "YAP1 is frequently upregulated and activated in different cancers including pancreatic cancer and contributes to tumor initiation and progression; however, there are few studies on YAP1 and its downstream targets and mechanisms." (PMID 31575084, 2019). "The results showed that NMU expression was highly correlated with YAP1 expression in pancreatic cancer." (PMID 31575084, 2019). "Here, we identified target genes regulated by YAP1 and explored their role in pancreatic cancer progression and the related clinical implications." (PMID 31575084, 2019). "A tissue microarray (TMA) containing 66 pancreatic cancer samples showed marked variation in YAP1 and NMU expression." (PMID 31575084, 2019). "We identified an association between NMU and YAP1 and provide in vivo and in vitro evidence supporting the essential role of NMU in YAP1-driven pancreatic cancer progression and metastasis." (PMID 31575084, 2019). "YAP1 is an oncoprotein involved in tumorigenesis in multiple types of cancer including pancreatic cancer." (PMID 31575084, 2019). "Analysis of different pancreatic cancer databases showed that Neuromedin U (NMU) expression was positively correlated with YAP1 expression in the tumor group." (PMID 31575084, 2019). "Taken together, our findings suggest that PKCι acts through promoting YAP1 function to promote the survival of pancreatic cancer cells expressing mu-Kras." (PMID 30214681, 2018). "It appears that targeting PKCι-YAP1 signaling is a feasible strategy for developing new therapeutics for treating pancreatic cancer patients." (PMID 30214681, 2018). "YAP1 can also act synergistically to promote pancreatic cancer progression by hyperactivation of AKT signaling." (PMID 28915618, 2017). "We also examine the expression level of YAP1 in a panel of eight human pancreatic cancer and two immortalized normal human pancreatic epithelial cell lines using Western blotting." (PMID 22396793, 2012). "We have determined that YAP1 is overexpressed in pancreatic tumor tissues, and the down-regulation of YAP1 abated proliferation and clonogenicity of cultured pancreatic cancer cells." (PMID 22396793, 2012). "YAP1 is overexpressed in pancreatic cancer tissues and potentially plays an important role in the clonogenicity and growth of pancreatic cancer cells." (PMID 22396793, 2012). "This expression profile of YAP1 in pancreatic cell lines is consistent with what we observed in the pancreatic tumor tissue samples." (PMID 22396793, 2012). "Since we observed a significant effect on cell proliferation, we wanted to consider if YAP1 knockdown by siRNA would abolish anchorage-independent growth of pancreatic cancer cells." (PMID 22396793, 2012). "In our study, we have observed that YAP1 is overexpressed in pancreatic tumors and in cancer cell lines." (PMID 22396793, 2012). "We examined the YAP1 protein expression and localization in pancreatic tumor tissues taken from patients with pancreatic cancer and investigated the phenotypic effects of YAP1 down-regulation in cultured pancreatic cell lines." (PMID 22396793, 2012). "To evaluate the effect of YAP1 inhibition on apoptosis, we measured the activation of caspase-3 and caspase-7 in pancreatic cancer cells treated with siRNA." (PMID 22396793, 2012). "Immunohistochemical staining of YAP1 protein was used to assess the expression of YAP1 in pancreatic tumor tissues." (PMID 22396793, 2012).
pancreatic cancer (continued). "Next, we correlated the activated nuclear YAP1 expression level with histopathological parameters in patients with pancreatic cancer." (PMID 22396793, 2012). "The subcellular localization of YAP1 in the pancreatic tumors and in the cultured cell lines highlighted the dysregulation of the Hippo pathway." (PMID 22396793, 2012). "In conclusion, our study shows that YAP1 is overexpressed in pancreatic cancer and offers a mechanistic insight into the phenotypic effect of the down-regulation of YAP1." (PMID 22396793, 2012). "Two pancreatic cancer cell lines (AsPC-1 and Capan-1) had undetectable to low YAP1 protein levels, respectively." (PMID 22396793, 2012). "Nuclear YAP1 expression level and its correlation with histopathological parameters in pancreatic cancer." (PMID 22396793, 2012). "Immunohistochemistry studies in pancreatic tumor tissues revealed YAP1 staining intensities were moderate to strong in the nucleus and cytoplasm of the tumor cells, whereas the adjacent normal epithelial showed negative to weak staining." (PMID 22396793, 2012). "Investigation of these upstream regulators of YAP1 in pancreatic cancer will shed further light on the role of Hippo pathway in the tumorigenesis and progression of pancreatic cancer." (PMID 22396793, 2012). "siRNA oligonucleotides were used to knockdown the expression of YAP1 and their effects on pancreatic cancer cells were investigated using cell proliferation, apoptosis, and anchorage-independent growth assays." (PMID 22396793, 2012). "Further investigation of YAP1 expression in xenograft tumors formed by the pancreatic cancer cell lines also showed similar results." (PMID 22396793, 2012). "The KH3-4 domain of the m6A reader proteins IGF2BP2 and IGF2BP3 specifically recognised the m6A-modified YAP1 transcripts, thereby stabilising YAP1 mRNA and increasing YAP1 protein expression, which in turn promoted colony formation and invasion in pancreatic cancer cells." (PMID 42231052, 2026). "At the same time, ATF5 prevents the growth of pancreatic cancer cells by promoting YAP1 expression." (PMID 40124511, 2025). "Similarly, pancreatitis-induced ADM cooperates with oncogenic KRAS to drive pancreatic cancer progression by activating YAP1/TAZ, which in turn upregulate JAK-STAT3 signaling, promoting PDAC development." (PMID 40707469, 2025). "Notably, zinc pyrithione (ZnPT) targets SDCBP, restoring YAP1 degradation and suppressing tumour growth in PDX and PDO models, indicating the SDCBP–YAP1 axis as a promising therapeutic target for pancreatic cancer." (PMID 41463025, 2025). "In pancreatic cancer, the overexpression of YAP1 may promote invasiveness, epithelial-mesenchymal transition (EMT), and resistance to gemcitabine." (PMID 38567163, 2024). "Furthermore, YAP1 activation is an important mechanism in driving pancreatic tumor growth in KRAS-independent PDAC recurrence." (PMID 38247878, 2024). "Our experiments showed that GPRC5A could bidirectionally control the expression of YAP1 and its target genes at the transcriptional level in pancreatic cancer cells." (PMID 36735162, 2023). "In pancreatic cancer, inhibition of the Hippo/YAP1/c-Jun axis could suppress cancer stemness and overcome drug resistance." (PMID 37752152, 2023). "Furthermore, our data showed that silencing YAP1 by siRNA disrupted the malignant biological behavior of GPRC5A in pancreatic cancer cells." (PMID 36735162, 2023). "Recently, YAP1 (a nuclear effector of an inactivated HIPPO pathway) has been recognized as a potent oncogene closely linked to the prognosis and progression of several types of cancer, including breast and pancreatic cancer." (PMID 37383164, 2023). "To investigate whether GPRC5A promoted pancreatic cancer progression via the YAP1 pathway, we evaluated the relationship between GPRC5A and YAP1 in pancreatic cancer tissues and cells." (PMID 36735162, 2023).